ISG15 (ISG15 ubiquitin like modifier)
Diseases named in the same sentence as ISG15 in open-access papers (continued):
Sharing a sentence is not in itself a finding about the gene and the disease.
infection (continued). "We found that infection with the IFN-sensitive RRV strain resulted in the robust induction of several well-defined ISGs, including those encoding IFIT1/2/3, ISG15, ISG20, RSAD2, and Mx2." (PMID 27128797, 2016). "Interferon-stimulated gene 15 (ISG15) is a cytokine secreted from monocytes and lymphocytes upon infection or the treatment of Type I interferon (IFN-α/β)." (PMID 27659523, 2016). "For ISAV, previous studies have indicated that a low-virulent strain induced the antiviral proteins Mx and ISG15 more potently than a high virulent ISAV strain early in the infection cycle in cell cultures." (PMID 26901217, 2016). "Infected cells were harvested at 12 and 24 h after infection, and the amount of ISG15 conjugates was measured using immunoblots." (PMID 27587337, 2016). "ISG15 has primarily been characterized, in the context of infection, as an antiviral protein induced by type I interferon." (PMID 26259872, 2015). "Following infection, ISG15-overexpressing cells secreted significantly more IL-8 than infected wild-type cells at both 3 and 7 hr post infection." (PMID 26259872, 2015). "Among the genes upregulated during infection is IFN-stimulated gene 15 (ISG15), a small ubiquitin-like protein that covalently attaches to lysine residues on target substrates through post-translational modification." (PMID 26361997, 2015). "The difference in IL-8 concentration in the media after 24 hr of infection was nearly threefold higher in ISG15-overexpressing cells relative to control cells." (PMID 26259872, 2015). "Further experiments found that ISG15 can counteract the infections of L. monocytogenes both in cells grown in cultures and in living mice." (PMID 26259872, 2015). "Following HCVcc infection at different m.o.i., sh6 cells maintained lower levels of ISG15 mRNA at 24 and 48 h post-infection compared with shCtrl cells." (PMID 26361997, 2015). "Strikingly, infection or overexpression of ISG15 leads to ISGylation of ER and Golgi proteins, which correlates with increased secretion of cytokines known to counteract infection." (PMID 26259872, 2015). "For the same multiplicity of infection (MOI) after 3 hr of infection, stable overexpression of ISG15 resulted in 50% fewer cytosolic bacteria as compared to control cells." (PMID 26259872, 2015). "We thus sought to determine how ISG15 was induced and what consequences ISG15 expression had on the cell and on infection." (PMID 26259872, 2015). "Infection with L. monocytogenes led to significantly higher IL-8 and IL-6 than L. innocua expressing InlB, which correlates with increased ISG15 expression." (PMID 26259872, 2015). "Isg15 is one of the strongest genes induced by type I interferons in response to cellular stress and infection." (PMID 23826213, 2013). "Whereas in ISG15+/+ macrophages, the synthesis of viral proteins was clearly detectable at 3 hpi, a clear delay in the course of infection and viral protein synthesis was observed in ISG15−/− macrophages." (PMID 24137104, 2013). "Although the role of ISG15 as a defense molecule against the infection by several pathogens is accepted, the mechanisms by which its antiviral properties are exerted and the main cellular populations responsible for these activities are still weakly defined." (PMID 24137104, 2013). "In cells transfected with control siRNA, Candid#1 JUNV infection led to induction of ISG15 protein expression and STAT1 phosphorylation as expected." (PMID 22629479, 2012). "So far, ISG15-mediated antiviral activity has been shown most convincingly in vivo by means of infections in ISG15−/− mice." (PMID 22272257, 2012). "Consistent with this, we recently documented a paucity of type I IFN-dependent ISG expression (e.g., IFIT-1, ISG15) within the liver of HAV-infected chimpanzees during the first weeks of infection despite high viral RNA copy numbers." (PMID 21931545, 2011).
infection (continued). "We establish a role for ISG15 in the pathogenesis of CHIKV infection with an absolutely essential role in the neonatal response to infection." (PMID 22028657, 2011). "After pretreatment with 25 μg of pIC, 14% of the ISG15−/− mice still succumbed to infection as compared to complete protection seen in the WT mice." (PMID 22028657, 2011). "A follow-up of the infection over a period of 96 hours showed that JFH1 was replicating correctly in those cells as well as leading to induction of ISG15 (10-fold) and to some induction of IFNβ (2.5-fold)." (PMID 22022264, 2011). "Infection of NSDV/GV resulted in a drastic decrease in ISG15-conjugates found in Vero cells when compared to uninfected cells." (PMID 22163042, 2011). "The rapid induction of ISG15 following IFN stimulation has led to the identification of an antiviral role for ISG15 during infection." (PMID 22028657, 2011). "Interferon-Stimulated Gene 15 (ISG15) expression was significantly induced upon infection by both MCMVΔ152 (Δ152) and UV-inactivated virus (UV), indicating that neither viral entry nor activation of the interferon response was affected by the UV treatment." (PMID 21966273, 2011). "The analysis of selected ISGs expressed at the site of infection revealed that ISG15 mRNA was rapidly and strongly induced during CHIKV infection." (PMID 22028657, 2011). "In ISG15 knock-down cells, the RIG-I/MAVS association occurred later at 6 hrs post-infection with an increase in TRAF3 association at 9–12 hrs post infection." (PMID 22022264, 2011). "Serum from WT, UbE1L−/− and ISG15−/− mice collected at 1 or 2 days post-infection were analyzed for IFNα as well as proinflammatory cytokines and chemokines." (PMID 22028657, 2011). "This indicates ISG15 and its conjugation play important roles in innate immunity and antiviral response to infection." (PMID 20569475, 2010). "Previously, using cDNA microarrays we described up-regulation of ISG15 after infection of HeLa cells with the attenuated VACV strains MVA and NYVAC, an effect not observed after infection with the virulent strain WR." (PMID 18604270, 2008). "Through the use of microarrays we identified the gene ISG15 as being induced in the course of infection of human cells with different strains of VACV." (PMID 18604270, 2008). "During infection of MEFs from ISG15 KO or ISG15 depleted cells, the presence of E3 enhances viral production since the WR titers are greater than those after infection with the VVΔE3L mutant virus." (PMID 18604270, 2008). "Although lung homogenates presented similar amounts of ISG15 protein, the conjugation of ISG15 to its targets proteins, was greatly enhanced after infection with VVΔE3L or VVE3LΔ26C." (PMID 18604270, 2008). "The biological significance of ISG15 mRNA induction in cultured cells after infection with the VACV mutants and its repression by the virulent WR is not known." (PMID 18604270, 2008). "The level of ISG15 mRNA expression was similar to the level of ISG15 protein expression at 24 h and 48 h pi where similar levels were observed following WT or ΔNS1/2 infection of MLE-15 cells." (PMID 18851747, 2008). "The role of ISG15 in VACV replication was also supported by the more abundant VACV infectious virus and viral proteins produced in lungs of ISG15−/− mice compared with lungs of ISG15+/+ mice after infection with WR or with the E3L deletion mutant viruses." (PMID 18604270, 2008). "One explanation is that ISG15 is made non functional after infection with these viruses, because the carboxy-terminal domain of E3 binds to ISG15 and blocks its activity." (PMID 18604270, 2008). "Infection studies using IAV suggest that the loss of cholesterol and PS from the plasma membrane in cells from ΔWD mice results in increased endocytosis and nuclear delivery of IAV, as well as increased Ifnb/Ifnβ and Isg15 gene expression." (PMID 40143422, 2025).
infection (continued). "Interestingly, like A549‐ISG15−/− cells, NP expression was undetectable at 24 h post‐infection in both ISG15.AA and ISG15.ΔGG‐expressing cells." (PMID 39931755, 2025). "While ISG15 may enhance the immune response during the early stages of infection, HIV-1 manipulates host immune pathways to reduce sustained interferon signaling, allowing the virus to persist in latently infected cells." (PMID 40284971, 2025). "Intriguingly, this gradient in viral protein expression is inversely correlated with the gradient observed for ISG expression, linking the ability of ISG15 and ISG15 mutants to regulate the magnitude of the antiviral response with their capacity to support infection." (PMID 39931755, 2025). "Similar immunomodulatory effects of ISG15 are seen during infection with M. tuberculosis." (PMID 41358638, 2025). "The transcription of ISG15 in epithelial cells is strongly upregulated by Ct infection, but the effects of ISG15 in the infected FGT are currently unknown." (PMID 40627782, 2025). "However, infection with VACV ΔE3L resulted in a 20–52-fold increase of either ISG15 or IFN-β mRNA levels detected in the presence of RIG-I compared to in the ΔRIG-I cells." (PMID 40258008, 2025). "Importantly, BTV replication in ovine cells led to the highest suppression of Ifnα and Isg15 transcription, in comparison with iBTV, which shows that the infection suppresses IFN induction mediated by DNA sensing." (PMID 39836220, 2025). "In Atlantic salmon, the ISG15 gene responds similarly to both interferon and infection by ISAV." (PMID 40630959, 2025). "Furthermore, we investigated the influence of Ct infection on the production of ISG15 in immune cells." (PMID 40627782, 2025). "Here we show that Ct-infection induces the secretion of ISG15 from primary host cells." (PMID 40627782, 2025). "Despite this observation, the role of extracellular ISG15 at different disease stages during infection remains unclear." (PMID 40719862, 2025). "Interestingly, significant upregulation of ISG15 was detected in the serum of human volunteers after administration of IFN-β or during infection." (PMID 40719862, 2025). "However, the comparatively lower ΔORF2 RNA level after internalization and the significant decrease until day 7 compared to WT RNA suggested a relatively stronger induction of IFNL1 and ISG15 expression in ΔORF2 infection." (PMID 40982567, 2025). "To investigate whether ISG15 is induced by Ct infection, we infected different human cell lines and primary cells or treated them with IFN-α, a known stimulator of ISG15 production." (PMID 40627782, 2025). "All three selected ISGs namely Mx1, IFIT3 and ISG15 were induced after infection with BADwt." (PMID 40143353, 2025). "On the other hand, ISG15 mRNA levels were downregulated in the p62 knockdown cells after USUV infection, suggesting that some ISGs might be affected by p62 signaling." (PMID 40247289, 2025). "This feature of NK cell localization further supports our hypothesis that secreted ISG15, induced by Ct infection in epithelial cells, signals to nearby NK cells to enhance the IFN-γ response." (PMID 40627782, 2025). "This is consistent with a role for ISG15 in the clearance of infection rather than the susceptibility of the host to infection." (PMID 40627782, 2025). "However, expression of the IFN-stimulated gene (ISG) IFIT2 was only slightly increased (less than 2-fold upregulation), while ISG15 levels were even downregulated during infection after p62-knockdown." (PMID 40247289, 2025). "During this phase of infection, when levels of pro-inflammatory cytokines (such as IL-18) are low, secreted ISG15 from infected epithelial cells can help NK cells to increase secreted IFN-γ levels, thereby enabling an earlier and more rapid response to the infection." (PMID 40627782, 2025). "As for PEDV, we have shown that ISG15 was highly induced upon infection." (PMID 40218394, 2025).
infection (continued). "In most cases in uninfected states, we observed that cells expressing only the empty vector (EV) showed a slight increase in expression of either ISG15 or IFN-β mRNA under mock infection conditions, consistent with an increased propensity for immune activation in the absence of DUSP11." (PMID 40258008, 2025). "In contrast, ISG15 transcription is induced within 6 h of infection." (PMID 39345209, 2024). "Also there are reports of ISG15 having an antiviral function independent of Ube1L during Chikungunya virus infection in mice, where free ISG15 contributes to infection control by blunting potentially pathologic levels of cytokine effectors." (PMID 38384473, 2024). "In contrast, the injection of the viral suspension triggers a more potent proinflammatory response characterized by a significant induction of both il1b and tnfa, associated with the activation of interferon signaling as shown by the upregulation of isg15 expression at late stages of infection." (PMID 39102417, 2024). "Robust ISG-15 elevation upon IFN challenge was observed at Day 90 compared to Day 0 in the uninfected, suggesting that this can be caused by either the vaccine or breakthrough infections." (PMID 39065157, 2024). "Indeed, we observed a strong induction of ISG15 expression by epithelial cells upon infection by C. trachomatis." (PMID 39345209, 2024). "Interestingly, ISG15 also regulates disease tolerance after the infection by activating the repair response of the respiratory epithelium, potentially through the reorganization of the cytoskeleton of actin." (PMID 39409176, 2024). "Low- and high-risk human papilloma virus (HPV) infections elicit differential ISG15 induction in the cervical mucosae of infected human patients, indicating that ISG15 may contribute to the innate response to infection in the female genital tract (FGT)." (PMID 39345209, 2024). "Additionally, it was reported that ISG15 expression was induced independently of IFN-I upon infection of epithelial cells by Listeria monocytogenes, a Gram-positive bacterium that developed in the cytoplasm." (PMID 39345209, 2024). "The data suggest a dual role for ISG15 in modulating the immune landscape in DM, in terms of M1 macrophages, when the infection or inflammation is severe enough to affect an organ, macrophages first exhibit the M1 phenotype to release TNF-α, IL-1β, IL-12, and IL-23 against the stimulus." (PMID 39559355, 2024). "Intriguingly, genes such as Ifi204, Irgm1/2, Nos2, Gbp3/7, Usp18, Irf7, Stat1, and Isg15, which were upregulated in response to infection in cells treated with siR_Ctrl, showed decreased upregulation in cells treated with siR_Nostrill following infection." (PMID 39040107, 2024). "All infected samples (Day 0 and Day 90) showed a significant increase in ISG-15, suggesting that the infection causes this sensitisation with or without vaccine influence." (PMID 39065157, 2024). "Infection of microglia was associated with a sharp increase in CCL2 and CXCL10 chemokine gene expression and the activation of many type I interferon stimulated genes (MX1, ISG15, ISG20, IFI27, IFITM3 and others)." (PMID 38737767, 2024). "In the context of human immunodeficiency virus type 1 (HIV-1) infection, a recent study shows that ISG15 deficiency exacerbates infection rates due to lack of ISGylation of the STING protein and suppression of the STING-dependent DNA sensing pathway." (PMID 38400136, 2024). "Although there was a trend of lower protein levels in infected Isg15−/− cells, neither the levels nor the distribution of any of the viral proteins analyzed significantly differed between Isg15−/− and Isg15+/+ MEFs, indicating that the infection occurred normally in both genotypes." (PMID 37036376, 2023). "Infection withL. monocytogenes provokes ISG15 modification at active sites and dimerization domains of metabolic enzymes, which could block their function." (PMID 37954520, 2023).
infection (continued). "In contrast, BA.5 infection upregulated Cxcl10, Isg15, and Mx-1 expression more than the other Omicron subvariants infection in the lung periphery area, suggesting that BA.5 might provoke severe inflammation, supporting the histopathological data." (PMID 37488344, 2023). "Limiting ISG15 secretion might be expected to be detrimental in combating the infection because pro-inflammatory cytokines are important in recruiting and activating cells of the adaptive immune response." (PMID 37298304, 2023). "ISG15 is a member of the ubiquitin family which is critical for the control of pathogen infections." (PMID 37684607, 2023). "The ONNV alone increased ISG15 mRNA expression 24 h post-infection (15-fold)." (PMID 37958918, 2023). "Infection of Isg15−/− mouse embryonic fibroblasts (MEFs) with VACV IHD-J resulted in reduced EV production, consistent with reduced actin tail formation, the accumulation of virus particles in the cytoplasm, and the abolition of comet-shaped plaques, compared to Isg15+/+ MEFs." (PMID 37036376, 2023). "On the other hand, if some of the most severe and deadly consequences of infection are the result of cytokine release syndrome, then limiting ISG15 secretion and signaling by therapeutically inhibiting PLpro might be beneficial." (PMID 37298304, 2023). "Furthermore, the temporal expression profiles of eight selected antiviral-related mRNA including IRF3, IRF7, IKKβ, TBK1, IFIT1, IFI44, MX1 and ISG15 were detected by qRT-PCR, which showed a significantly stronger response at early infection under 20 °C." (PMID 37627029, 2023). "Limiting ISG15 secretion might be expected to be detrimental in combating the infection because pro-inflammatory cytokines are essential in recruiting and activating cells of the adaptive immune response." (PMID 37298304, 2023). "highlighted the importance of two cysteine domains in the hinge region on ISG15, which are essential for dimer formation and for its cytokine activity, probably involved in the inflow of IL-1β–producing CD8αDCs to the site of infection." (PMID 37313341, 2023). "On the other hand, if some of the most severe and deadly consequences of infection are a result of cytokine release syndrome, then limiting ISG15 secretion and signaling by therapeutically inhibiting PLpro might be beneficial." (PMID 37298304, 2023). "To further confirm whether the decrease in ISG15 and IFN-γ is caused by the activation of LRRC25, we quantified the mRNA of ISG15 in the four groups of cells before and after transfection and before and after infection." (PMID 37894158, 2023). "Infection of Isg15−/− mouse embryonic fibroblasts with VACV International Health Department-J (IHD-J) strain resulted in decreased EV production, concomitant with reduced induction of actin tails and the abolition of comet-shaped plaque formation, compared to Isg15+/+ cells." (PMID 37036376, 2023). "This notable result indicated that unchecked covalent modification by ISG15 could lead to an intracellular accumulation of GML following infection or starvation." (PMID 37954520, 2023). "Therefore, we can conclude that MVA-Δ3-ISG15AA virus is a strong IFN-I inducer and, consequently, an ISG15 and ISGylation enhancer during in vivo infection." (PMID 37313341, 2023). "The same response was also monitored with RT-qPCR in an in vitro controlled infection trial, in which the IFN-regulated antiviral genes Mx and ISG15 were strongly upregulated in gills throughout the infection course with a higher induction in the group suffering severe disease and mortality." (PMID 36560705, 2022). "The results show that the ISG15-/- mice displayed typical neurological symptoms, including considerably reduced activity and pruritus at 3 days post infection (dpi), with death beginning at 4 dpi, whereas WT mice developed only mild symptoms at 5 dpi under the same conditions." (PMID 36146669, 2022). "Similar results were obtained from a parallel transfection / infection in ISG15-/- cells." (PMID 36315588, 2022).